GAPDH (glyceraldehyde-3-phosphate dehydrogenase)
Diseases named in the same sentence as GAPDH in open-access papers (continued):
Sharing a sentence is not in itself a finding about the gene and the disease.
cancer (continued). "Deimination of GAPDH may contribute to its multifaceted physiological functions, and the identification of its deimination in several taxa with unusual metabolism and cancer resistance is of considerable interest." (PMID 32411128, 2020). "Targeting MCTs and GAPDH under different microenvironments reduces the cancer cell’s viability." (PMID 33379345, 2020). "GAPDH has been shown to be regulated via some posttranslational modifications and was recently identified as a deimination candidate by our group in cancer, as well as in whales and to form part of deiminated protein EV cargo in naked mole rat plasma." (PMID 32411128, 2020). "It has been hypothesized that high concentrations of vitamin C may inhibit the GAPDH pathway, leading to an energy crisis in cancer cells." (PMID 33292305, 2020). "Furthermore, GAPDH deregulation has been detected in several cancer types such as lung, renal, breast, gastric, and pancreatic cancer, thus suggesting a potential role in tumor progression." (PMID 33584695, 2020). "Additionally, a number of reports offer an obvious link between a high level of active GAPDH tetramer, the elevated mobility of cancer cells, and the markers of the epithelial-mesenchymal transition." (PMID 32370188, 2020). "Finally, also GAPDH is a potential cancer therapeutic target as well, since inhibition of this glycolytic enzyme by 2-DG inhibits cancer cell growth." (PMID 33008042, 2020). "Furthermore, in the same cancer type the production of ROS by inhibition of the antioxidant mitochondrial uncoupling protein 2 (UCP2) stimulates the nuclear translocation of GAPDH which promotes autophagy." (PMID 31027346, 2019). "Thus, inhibiting GAPDH activity can be considered a therapeutic opportunity for the blockage of cancer cell metabolism counteracting the high glycolytic flux of cancer cells." (PMID 31027346, 2019). "The three investigated cell types had high cytosolic levels of GAPDH and could be clearly differentiated by their expression levels of Gal-3 and Gal-3bp, which are important factors that contribute to cancer metastasis." (PMID 31700673, 2019). "In addition, cells treated with a concentration of 2.5 ng/mL of gold nanoparticles demonstrated degradation of GAPDH (glyceraldehyde-3-phosphate dehydrogenase), which is known to be over-expressed in cancer." (PMID 31024882, 2019). "The significant downregulation of GAPDH by the combination therapy could explain the notable enhancement of cancer cell cytotoxicity." (PMID 31612140, 2019). "Interestingly, the elevated ROS levels result in an inactivation of glyceraldehyde-3-phosphate dehydrogenase (GAPDH) which ultimately leads to an energetic crisis that kills these highly glycolytic cancer cells." (PMID 31434226, 2019). "It has been shown previously that GAPDH depletion accelerates cellular senescence of a cancer line." (PMID 30788732, 2019). "Several molecular mechanisms may trigger or prevent GAPDH nuclear translocation to regulate autophagic events particularly in cancer." (PMID 31027346, 2019). "Finally, we propose that the modulation of the subcellular localization of GAPDH can be considered a potential target mechanism in autophagy regulation for cancer therapy." (PMID 31027346, 2019). "Consequently, it was applied in the down-regulation of endogenous genes (BCL2 and GAPDH) of the human cancer cell, showing that TX-2 knocked down expression of the target genes much more effectively than WT-HHRz in both mRNA and protein level." (PMID 30649474, 2019).
cancer (continued). "Continuous replenishment of NAD promotes the proliferation and survival of fast-dividing cancer cells because elevated NAD levels enhance glycolysis via glyceraldehyde 3-phosphate dehydrogenase (GAPDH) and lactate dehydrogenase (LDH) that require NAD as a co-enzyme." (PMID 30631755, 2018). "This is also the case for GAPDH, whose role in cancer prognosis is uncertain." (PMID 30241282, 2018). "Deregulation in the expression level of GAPDH are found in many cancer cells." (PMID 28704482, 2017). "There are signs of involvement of GAPDH in cancer progression and it may serve as a new marker or even a therapeutic target." (PMID 28704482, 2017). "With P-gp and GAPDH as a model, satisfactory performances were achieved to identify the drug resistance of the cancer cells based on the proposed ECL assay, which was fitted well with the theory line with a correlation coefficient of 0.9928 and a detection limit of 0.52%." (PMID 28451145, 2016). "Molecular mechanism behind MG mediated GAPDH inhibition in cancer cells is not well understood." (PMID 26911935, 2016). "Association of GAPDH with PKM2 and GPI may give a special advantage for cancer cell metabolism and survival." (PMID 26911935, 2016). "FK866 has been shown to exert strong effects on cancer cell metabolism, such as glycolysis, pentose phosphate pathway, tricarboxylic acid cycle, serine biosynthesis and attenuating glycolysis at the glyceraldehyde 3-phosphate dehydrogenase step due to reduced availability of NAD+ for the enzyme." (PMID 27462772, 2016). "One attractive novel approach for targeting cancer cells, derived from the present study, which deserves further experimental assessment, is the use of inhibitors of GAPDH, ENO, and PYK together with glyoxylase inhibitors, which at relatively low doses do not perturb host homeostasis." (PMID 27721794, 2016). "We also found that GAPDH inhibited the growth of several cancer cell lines." (PMID 25785838, 2015). "PTMs play important roles in regulating diverse GAPDH functions in cancer cells." (PMID 25859407, 2015). "As an important glycolytic enzyme, GAPDH participates in cancer cell proliferation." (PMID 25859407, 2015). "As a multifunctional protein, GAPDH also influences cancer cell fate." (PMID 25859407, 2015). "Furthermore, diverse GAPDH-related PTMs, which influence the functions of this enzyme in cancer cells, are identified." (PMID 25859407, 2015). "A previous analysis indicated that intracellular GAPDH could be secreted in the CM of some mammalian cell lines including cancer cell lines and might induce cell morphological change or inhibit cell spreading." (PMID 26338966, 2015). "That is, cancer cells differ in their sensitivities to IL-6 and also GAPDH." (PMID 25785838, 2015). "However, the effects of these inhibitors of GAPDH S-nitrosylation on human cancer cells remain obscure." (PMID 25859407, 2015). "However, emerging evidence indicates that GAPDH is implicated in diverse functions independent of its role in energy metabolism; the expression status of GAPDH is also deregulated in various cancer cells." (PMID 25859407, 2015). "Glyceraldehyde-3-phosphate dehydrogenase (GAPDH) is overexpressed in cancer and may promote resistance to chemotherapy by inducing Bcl-xL overexpression." (PMID 25693144, 2015). "We previously reported NQO1-dependent, ROS-induced S-nitrosylation and nuclear translocation of GAPDH in various NQO1 cancer cells after β-lap treatment, and reactive nitrogen species-mediated irreversible inhibition of GAPDH has also been previously shown in vitro." (PMID 25590809, 2015). "In addition, this mechanism partially explains the overexpression of GAPDH in some cancer cells at mRNA and protein levels." (PMID 25859407, 2015).
cancer (continued). "Therefore, these deregulations of GAPDH in cancers indicate the inconsistent roles of this enzyme in cell fate determination." (PMID 25859407, 2015). "It covalently binds to the glycolytic enzymes; hexokinase-2, Glyceraldehyde-3-phosphate dehydrogenase and mitochondrial; succinate dehydrogenase, in addition, to the endoplasmic reticulum and the lysosomes resulting in severe depletion in ATP and cancer death." (PMID 26526196, 2015). "Despite this knowledge, the roles of GAPDH as a chaperone in cancer cells remain poorly understood." (PMID 25859407, 2015). "However, GAPDH is reported to be involved in biological processes and GAPDH expression is substantially increased in human cancers from the cervix, prostate, pancreas and lung, and in MCF7 cells treated with oestradiol." (PMID 25617865, 2015). "Most cancer cells exhibit increased glycolysis and use this metabolic pathway for generation of ATP as a main source of their energy supply and GAPDH may be a potential target for cancer intervention." (PMID 25691059, 2015). "In HeLa cells, GAPDH enhances mitophagy and induces cancer cell survival." (PMID 25859407, 2015). "GAPDH is also involved in various diseases especially neurodegenerative disorders and cancers." (PMID 25646800, 2015). "Moreover, posttranslational modifications (PTMs) occurring in GAPDH in cancer cells result in new activities unrelated to the original glycolytic function of GAPDH." (PMID 25859407, 2015). "We propose that negative regulation of cancer growth using GAPDH could be a new anti-cancer strategy." (PMID 25785838, 2015). "Considering these reports, LL-37 can be associated with dual aspects of cancer progression via various receptors, such as epidermal growth factor receptor (EGFR), FRP2, ERBb2, P2X7, and GAPDH, or suppression via interaction with peptide-based factors and cancer membrane components." (PMID 26175965, 2015). "All genes studied achieved medium expression stability with M values ranging from 1.09 for B2M to 0.82 for GAPDH (average geNorm M≤1.0), which is typically seen when evaluating candidate reference targets on heterogeneous samples, like cancer biopsies or samples from different tissues." (PMID 25473950, 2014). "However, the β-subunit of H+/K+-ATPase was equally expressed in all the cancer cell lines, based on the similar expression level of total proteins controlled by GAPDH." (PMID 25202402, 2014). "Taken together, these results suggest that nanoliposomal C6-ceramide could be an effective novel therapy for patients whose cancer cells overexpress GAPDH, including those with CLL." (PMID 24367685, 2013). "In addition, 3-BrPA shows utmost specificity and selectivity for GAPDH both in vitro in multiple cell lines and in vivo in numerous animal models of cancer." (PMID 24298908, 2013). "However, this practice has recently been challenged due to findings of GAPDH playing a role in cancer pathogenesis." (PMID 24252137, 2013). "Inhibition of GAPDH triggers a cascade of events that eventually leads to cancer cell death." (PMID 24298908, 2013). "Moreover, GAPDH has been shown to be upregulated in many cancers and is the primary target of some chemotherapeutic drugs." (PMID 24367685, 2013). "The results suggest that transcription of GAPDH in tumors is an important step in cancer development, where it may contribute to increased cell cycle-related cell proliferation." (PMID 23620736, 2013). "Moreover, treatment with koningic acid, an inhibitor of GAPDH selectively induces cell death in cancer via ATP deprivation." (PMID 24367685, 2013). "It has been suggested that GAPDH overexpression may assist cancer cells in evading apoptosis and cell death mechanisms." (PMID 24367685, 2013). "Although the gene encoding glyceraldehyde-3-phosphate dehydrogenase (GAPDH) is frequently used as a stable marker for constitutive gene expression, its expression is not always constant, especially in cancer." (PMID 23620736, 2013).
cancer (continued). "In cancer, down-regulation of FBP1 can result in GAPDH accumulation within the cytoplasm and may also cause translocation of excess GAPDH to the nucleus." (PMID 23620736, 2013). "Conversely cancer tissues seem to gain an improved control on oxidative damage as shown by the selective reduction of carbonyl adducts on key detoxifying/pro-survival proteins such as ERp57, Anx2, Serpin B3, Pin1 and GAPDH." (PMID 22470562, 2012). "Conceivably, GAPDH inhibition could sensitize the cancer cells for chemotherapy, as the protection and resistance offered by GAPDH will also be abrogated." (PMID 22964488, 2012). "In the glycolysis pathway, all genes showed higher expression levels in cancer cell lines; and most notably, digital gene expression of glyceraldehyde-3-phosphate dehydrogenase (GAPDH) and enolase (ENO) were considerably increased when compared to the brain sample." (PMID 22166000, 2011). "Thus, binding of Bt18 parasporal protein to GAPDH is a significant finding as literature shows that there have been limited studies on identification of a binding protein for parasporins in cancer cells." (PMID 21073742, 2010). "Future gene therapy against cancer specific GAPDH isozymes might be another form of treatment in cancer." (PMID 21073742, 2010). "Because of the inverse association with lymph node metastasis, the relative levels of GPR30 to GAPDH could be applied as a marker to determine the cancer cell invasion." (PMID 21655374, 2008). "GAPDH was also suggested to play a role in the pathogenesis of cancer." (PMID 19014639, 2008). "However, GAPDH has been shown to be up-regulated in many cancers and down-regulated by chemotherapic drugs." (PMID 16515701, 2006). "We believe that the total number of cancer cells represented by CEA mRNA rather than the ratio of cancer/noncancer cells (CEA/GAPDH ratio) is a more important hallmark for predicting peritoneal recurrence." (PMID 16205696, 2005). "Furthermore, amino-BP have been reported to inhibit the synthesis of GAPDH in cancer cell lines." (PMID 41226655, 2025). "Similarly, when the effect of varied hypoxic conditions was evaluated in two cancer and two normal cell lines, a tremendous variation in the expression of the majority of 10 frequently used normalizers was found, again with GAPDH being one of the most variable HKGs." (PMID 40943534, 2025). "Metabolomic studies have been conducted in breast and colorectal carcinoma cells following administration of high-dose vitamin C. These studies consistently demonstrated an accumulation of metabolites upstream of glyceraldehyde 3-phosphate dehydrogenase (GAPDH) within the glycolytic pathway." (PMID 41300532, 2025). "Based on our comprehensive analysis of GAPDH using this tool, we found that both GAPDH protein and RNA levels are significantly upregulated in various cancers, suggesting that GAPDH may act as an oncogene, consistent with our previous analyses using the TCGA database." (PMID 38928396, 2024). "In this regard, studying the modulatory effects of miRNAs and lncRNAs on those glycolytic proteins linked with cancer progression, e.g., HK1, GAPDH, PKM2, GLUT1, GLUT3, HIF-1α, CAV1, Ras, HK2, LDHA, PGI/AMF, and PFKFB3, might be very favorable for the design of novel treatments for PC." (PMID 36332600, 2023). "However, it is unclear whether GAPDH-mediated iron uptake has any role in ferroptosis: cancer cells might utilize iron to favor their progression and to increase their invasive capability." (PMID 38001941, 2023). "Besides Gro3P and 2-PG, PGP/G3PP has also been shown to detoxify certain toxic glycolytic side products in cancer cell lines, particularly 4-phosphoerythronate and 2-phospholactate, produced by glyceraldehyde 3-phosphate dehydrogenase and pyruvate kinase, respectively." (PMID 35017476, 2022).
cancer (continued). "In conclusion, we recommend GAPDH as the most suitable reference gene in platelets for pan-cancer normalization, providing a reference standard for quantitatively detecting the gene expression levels in platelets for the diagnosis of pan-cancer by using this reference gene as an internal control." (PMID 35770000, 2022). "Since the Warburg effect can support aggressiveness and drug resistance of cancer cells, we further investigated whether the GAPDH inhibitor AXP-3019 may determine antiproliferative synergism with gemcitabine (GEM), an inhibitor of DNA polymerization used as standard treatment in PDAC patients." (PMID 35804925, 2022). "Yamaji reported that GAPDH was secreted by some cancer cells and could inhibit cell proliferation." (PMID 33953786, 2021). "The alteration of the expression level of GAPDH gene in sea urchin could be considered a suitable bioindicator for human health since its up-regulation was detected in cervical and ovarian tissue during cancer development." (PMID 34830379, 2021). "Importantly, ornidazole (a 5-NI) has been reported to inhibit GAPDH activity in mouse spermatocytes, protozoa and anaerobic bacteria, and depletion of GAPDH has also been reported to induce cytostatic effects on human cancer cell lines." (PMID 33640700, 2021). "This is consistent with data on the control of the overactive glycolytic flux in cancer cells, where GAPDH was also identified as the rate-limiting step in the pathway and the level of Fru1,6bisP found to be predictive for the rate and control of glycolytic flux at GAPDH." (PMID 33109759, 2020). "Interestingly, since autophagy might have a role in the promotion of cancer cell survival, GAPDH may act as a prosurvival factor in cancer through the induction of autophagy to support the energy consumption by rapid cell proliferation." (PMID 31027346, 2019). "In order to preserve the heterogeneities among tumors to the most extent, ACTB and GAPDH were avoided using as reference genes due to the fact that cytoskeleton and energy metabolism might be greatly deregulated among cancer individuals (Xiang, Chen & Fu, 2017; Stine & Dang, 2013)." (PMID 29915691, 2018). "Interestingly, over-expression of GAPDH has been observed in many types of cancers." (PMID 28446878, 2017). "Furthermore, apart from GAPDH another glycolytic enzyme upregulated is alpha-enolase which is now used as a potential cancer prognostic marker and promotes invasion in cancer cells indicating promotion of invasion by hTERT via regulation of these glycolytic enzymes." (PMID 28704482, 2017). "Association of GAPDH with PKM2 and GPI could be a signature for cancer cells." (PMID 26911935, 2016). "Thus, the mechanism by which GAPDH inhibits mTOR-p70S6K pathway through E-cadherin is still unknown, but GAPDH is newly rediscovered as an anti-cancer strategy." (PMID 25785838, 2015). "In addition, GAPDH is a protein target of saframycin A to decrease cancer cell proliferation." (PMID 25859407, 2015). "Indeed, glycolysis-related factors, including GAPDH, are essential for cancer cells." (PMID 25859407, 2015). "Despite the presence of GAPDH-PKCι/λ-Rab2 in cancer cells, functions of the complex remain unclear." (PMID 25859407, 2015). "PKCδ-induced phosphorylation of GAPDH may be inhibited in cancer cells to induce survival." (PMID 25859407, 2015). "Thus, GAPDH may be a critical regulator of cancer cell functions and a marker of cancer cell progression and prognosis." (PMID 25859407, 2015). "Therefore, measurement of the relative expressions of β-F1-ATPase and glyceraldehyde-3-phosphate dehydrogenase may have prognostic value for breast and other cancers." (PMID 25019059, 2014).